DNMT1 (DNA methyltransferase 1)
Diseases named in the same sentence as DNMT1 in open-access papers (continued):
Sharing a sentence is not in itself a finding about the gene and the disease.
congenital heart disease (3 papers, 2022 to 2023). A heart disease that is present at birth. "Further, a study in southeastern Iran found that the AG (heterozygous) genotype at rs6999593 in DNMT1 was strongly correlated with the susceptibility to and severity of congenital heart diseases, notably ventricular septal defects and TOF, suggesting its potential as a biomarker of disease." (PMID 37947606, 2023). "Furthermore, our group found that miR-328 was down-regulated via DNA methylation mediated by DNA methylation transferase 1 (DNMT1) in PASMCs stimulated with PDGF and in serum of PH patients associated with congenital heart disease (CHD-PAH)." (PMID 35454085, 2022).
gastric tumor (3 papers, 2020 to 2023). "Neck cell differentiation-related group C contained TFs such as Hes1, Pbx1, and Spdef, whereas isthmus progenitor cell-related group D again contained gastric tumor-related TFs such as Dnmt1 and Foxm1." (PMID 37386010, 2023). "Moreover, it has been found that DNMT1 overexpression is correlated with stomach tumor localization, DNMT3 overexpression is correlated with the tumor-node-metastasis (TNM) score, and the concomitant overexpression of DNMT1 and DNMT3A is significantly associated with lymph node metastasis." (PMID 37894343, 2023).
Glucose intolerance (3 papers, 2015 to 2021). Glucose intolerance (GI) can be defined as dysglycemia that comprises both prediabetes and diabetes. "In another study, methylation of the adiponectin promoter by DNMT1 reduced adiponectin expression in obese mice, and DNMT1 inhibition increased insulin sensitivity and ameliorated glucose intolerance." (PMID 34638914, 2021).
intestinal tumors (3 papers, 2016 to 2022). "We have shown previously that combinations of Dnmt1 hypomorphic alleles result in suppression of intestinal tumor formation in the ApcMin/+ model of intestinal neoplasia commensurate with decreasing Dnmt1 expression levels." (PMID 35873672, 2022). "Our present results show that pharmacologic and genetic DNA demethylation by 5-Aza-CdR treatment and Dnmt1 knockdown suppresses the proliferation of Apc-deficient intestinal tumor organoids." (PMID 27143627, 2016). "To investigate the effect of DNA demethylation on tumor organoids, we have established organoids from intestinal tumors of ApcMin/+(Min) mice and subjected them to 5-aza-2′-deoxycytidine (5-Aza-CdR) treatment and Dnmt1 knockdown." (PMID 27143627, 2016). "Furthermore, unlike Dnmt1 hypomorphic mice in which DNA hypomethylation suppresses the incidence of macroscopic intestinal tumors but promotes the formation of microadenoma in ApcMin/+ background, Uhrf1ki/ki/ApcMin/+ mice have markedly reduced incidence of both microadenoma and macroadenoma." (PMID 33947834, 2021).
leiomyoma (3 papers, 2021 to 2026). A well-circumscribed benign smooth muscle neoplasm characterized by the presence of spindle cells with cigar-shaped nuclei, interlacing fascicles, and a whorled pattern. "Fib-EXO increased the expression of vimentin, EZH2, DNMT1, TGF-β3, and c-MYC, and phosphorylated p65 protein, reduced COL1A1 and COL3A1 expression, and decreased miR-133a, miR-29, and miR-200c while increasing miR-21 in cultured myometrial smooth muscle cells, mirroring changes observed in fibroids." (PMID 42008339, 2026). "Thus, LINC00337 may be involved in the stimulation of cell proliferation in leiomyomas, since leiomyomas express higher levels of E2F1, EZH2, and DNMT1." (PMID 38279317, 2024).
male infertility (3 papers, 2017 to 2022). The inability of the male to effect fertilization of an ovum after a specified period of unprotected intercourse. "Under the recessive model of inheritance, the DNMT1 AA genotype was associated with significantly decreased risk for male infertility with abnormal semen parameters (adjusted OR, 0.68, 95% CI = 0.50–0.92, P = 0.012), compared with other genotypes." (PMID 28894282, 2017). "We show that variants in the DNMT3B and DNMT1 may have different relationships with idiopathic male infertility." (PMID 28894282, 2017). "When the DNMT1 CC genotype was used as the reference group, the CA genotype was significantly associated with increased risk for male infertility in Case Group I (adjusted OR, 1.50, 95% CI = 1.00–2.25, P = 0.048) and Case Group II (adjusted OR, 1.40, 95% CI = 1.05–1.86, P = 0.023)." (PMID 28894282, 2017). "The purpose of this study was to investigate the association between male infertility and single-nucleotide polymorphisms (SNPs) of DNA methyltransferases (DNMT) genes (DNMT3B: rs2424909, DNMT1: rs4804490, DNMT3A: rs1550117 and DNMT3L: rs7354779)." (PMID 28894282, 2017). "Variants of DNMT1 and DNMT3B are risk factors for idiopathic male infertility." (PMID 28894282, 2017).
mantle cell lymphoma (3 papers, 2020 to 2022). Mantle cell lymphoma is a rare form of malignant non-Hodgkin lymphoma affecting B lymphocytes in the lymph nodes in a region called the ``mantle zone''. "The expression of DNMT1 is up regulated in mantle cell lymphoma (MCL) and can be inhibited by DNMT inhibitor decitabine." (PMID 35463343, 2022). "In addition, a significant study on the mechanism of treatment for mantle cell lymphoma (MCL) indicated that the inactivation of the Wnt/β-catenin signaling pathway and downregulation of DNMT1 synergistically suppressed MCL, and these results could guide the dosing in the clinical treatment of MCL." (PMID 36091786, 2022).
meningioma (3 papers, 2013 to 2024). A generally slow growing tumor attached to the dura mater. "It is conceivable that DNMT1 is recruited by PRC component protein such as EZH2 to induce DNA hypermethylation in malignant meningiomas." (PMID 23349797, 2013). "Increased expression of the DNA methytransferase DNMT1 gene in malignant meningiomas suggests that DNMT1 may be involved in maintaining focal DNA hypermethylation, as other studies have reported in cancer cells." (PMID 23349797, 2013). "Expression of DNA methyltransferase such as DNMT1 gene is elevated in malignant meningiomas." (PMID 23349797, 2013).
non-alcoholic fatty liver disease (3 papers, 2021 to 2025). "During investigations of the effects of high extracellular glucose on the regulation of genes involved in non-alcoholic fatty liver disease, it was discovered that elevated 25-HC promoted methylation of CpG islands, acting as a direct, endogenous agonist of DNA methyltransferase 1 (DNMT1)." (PMID 34440846, 2021).
pituitary adenomas (3 papers, 2021 to 2024). "The passive demethylation event involves GC-induced hypomethylation through down-regulation of DNMT1 expression, described in a pituitary adenoma cell line." (PMID 39062828, 2024). "For instance, DNMT1 and DNMT3a upregulation aggravates the hypermethylation of antitumor genes in human pituitary adenomas." (PMID 34632937, 2021).
preeclampsia (3 papers, 2015 to 2026). Preeclampsia is a hypertensive disorder of pregnancy that is characterized by new-onset hypertension with proteinuria presenting after 20 weeks of gestation, and depending on mild or severe forms may initially present with severe headache, visual disturbances, and hyperreflexia. "Therefore, we suggest the regulation of global methylation via DNMT1 and DNMT3A and their dysregulation in preeclampsia under lower folate levels." (PMID 35578613, 2022).
pulmonary hypertension (3 papers, 2023). Increased pressure within the pulmonary circulation due to lung or heart disorder. "We recently reported that DNMT1 expression and activity are increased in the lungs of WT rats with induced pulmonary hypertension, but that effect was suppressed in G6PDS188F variant rats." (PMID 38069050, 2023). "In line with increased methylation levels, they also found that DNMT1 and DNMT3B were overexpressed in FHR lungs, which caused them to spontaneously develop pulmonary hypertension." (PMID 37461108, 2023). "A recent study found upregulated DNMT1 and DNMT3B expression and increased DNMT activity in the lungs of rats with sugen5416/hypoxia-induced pulmonary hypertension." (PMID 37947606, 2023).
rhabdomyolysis (3 papers, 2016 to 2025). Necrosis or disintegration of skeletal muscle often followed by myoglobinuria. "In LPS-induced rat models, procainamide treatment not only inhibits the overexpression of DNMT1 but also reduces the excessive production of IL-6 in rats with rhabdomyolysis, thereby improving renal function." (PMID 40766066, 2025). "Procainamide administration attenuated the increases of DNMT1 levels in the lungs of rats with rhabdomyolysis." (PMID 26918767, 2016). "Overt DNA methylation and IL-6 production were significantly improved after treatment of LPS-induced rhabdomyolysis rats with DNMT1 inhibitor procainamide, indicating a crucial role of DNA methylation in the accumulation of pro-inflammatory cytokines." (PMID 26918767, 2016). "In our previous study, the antiarrhythmic drug procainamide inhibits the expression of DNA methyltransferase 1 (DNMT1) and diminishes IL-6 levels in rats with rhabdomyolysis." (PMID 27661616, 2016). "The increases of lung DNMT1 expression and plasma IL-6 concentration were also observed in rhabdomyolysis animals induced by LPS." (PMID 26918767, 2016). "The rats in the LPS-induced rhabdomyolysis group only exhibited significant elevations of DNMT1 levels in the lung." (PMID 26918767, 2016). "Our results provide in vivo evidence that LPS could induce DNMT1 overexpression and IL-6 overproduction resulting in clinical manifestations of rhabdomyolysis which can be improved with procainamide treatment." (PMID 26918767, 2016). "In addition, our previous study also showed that procainamide could improve the syndromes and complications of rhabdomyolysis through the inhibition of DNMT1." (PMID 27661616, 2016). "Therefore, we suggest that DNMT1 inhibitors (e.g. procainamide) could be promising drugs for ameliorating serious complications in LPS-induced rhabdomyolysis." (PMID 26918767, 2016).
seminoma (3 papers, 2013 to 2018). A radiosensitive malignant germ cell tumor found in the testis (especially undescended), and extragonadal sites (anterior mediastinum and pineal gland). "Activating KIT mutations may lock KIT mutant seminoma cells into a PGC-like state in which UHRF1 and DNMT1 expression are suppressed, preventing the development of NSGCT components, which appear to require DNA methylation capacity." (PMID 29898407, 2018). "Seminomas and the seminoma-like cell line TCam-2 seem to utilize the replication dependent maintenance DNA methylation pathway since they display high DNMT1 expression and low/absent DNMT3A/B/L levels." (PMID 24386123, 2013).
skin aging (3 papers, 2017 to 2025). The gradual irreversible changes in structure of skin that occur as a result of the passage of time.. "Identification of the roles of miR-377 and DNMT1 in skin fibroblast senescence would facilitate the identification of potential new targets or drugs to prevent or cure skin aging." (PMID 28277545, 2017). "This study provides the first demonstration that miR-217 can induce senescence by targeting DNMT1 in relation to skin aging." (PMID 28380423, 2017). "Adaptive regulation of miR-217 and DNMT1 merits further in vivo research in the field of skin aging." (PMID 28380423, 2017). "Finally, we demonstrated an inverse correlation between DNMT1 and miR-217 expression in skin tissues and HSFs from patients of different ages, implying that miR-217 and DNMT1 contribute to the pathogenesis of skin aging." (PMID 28380423, 2017). "Finally, we demonstrated a negative correlation between miR-217 and DNMT1 expression during skin aging in vivo, implying that miR-217-dependent regulation of DNMT1 may occur in vivo and contribute to the pathogenesis of skin aging." (PMID 28380423, 2017). "Therefore, we speculated that DNMT1 might play a key role in skin aging." (PMID 28380423, 2017).
systemic sclerosis (3 papers, 2015 to 2023). A chronic disorder, possibly autoimmune, marked by excessive production of collagen which results in hardening and thickening of body tissues. "Although one might expect an increase in DNMT3a or DNMT3b to be primarily involved in initiating pro-fibrotic DNA methylation patterns, studies in the liver, lung, heart, kidneys and systemic sclerosis have implicated a role for elevated DNMT1 and/or DNMT3 or DNMT3b in fibrosis." (PMID 26435749, 2015). "In terms of epigenetic modulators, the increased expression of DNA methyltransferases 3A and 1 (DNMT3A and DNMT1) was observed in TGFβ–activated fibroblasts from fibrotic skin patients with systemic sclerosis (SSc), a prototypical idiopathic fibrotic disease." (PMID 37569677, 2023).
adenomyosis (2 papers, 2021 to 2024). The growth of endometrial tissue inside the muscular wall of the uterine corpus. "Studies on the expression and localization of DNMT in healthy females and those with adenomyosis revealed heightened immunoreactivity to DNMT1 and DNMT3B in ectopic endometrium, whereas DNMT3A staining levels significantly decreased in both eutopic and ectopic endometrium." (PMID 39345884, 2024). "Compared to endometrium from women without disease, women with adenomyosis had a significantly higher ectopic expression of DNMT1 (p = 3.2 × 10–6) and DNMT3B (p = 0.002) whereas DNMT3A (p = 4.1 × 10–6) was significantly reduced in both eutopic and ectopic endometrium." (PMID 35153815, 2021).
age-related macular degeneration (2 papers, 2023 to 2025). Age-related loss of vision in the central portion of the retina (macula), secondary to retinal degeneration. "DNMT1 has also been used in several studies as a biomarker of age-related macular degeneration." (PMID 37199639, 2023).
alcoholic hepatitis (2 papers, 2017 to 2019). Acute hepatitis resulting from ingestion of alcohol. "DNMT1 and DNMT3B (DNA-(cytosine-5) methyltransferase 1 and 3B) mRNA levels were markedly upregulated in the alcoholic hepatitis patients." (PMID 28208700, 2017).
alcoholism (2 papers, 2012 to 2018). "Contrary to the previous report on cell line study; our animal experiments revealed that, DNMT1 and DNMT3a protein levels were significantly decreased in brain tissue of mice under alcoholism and exercise restored their levels back to normal." (PMID 29581524, 2018). "The results revealed that, DNMT1 and DNMT3a protein levels were significantly decreased under alcoholism when compared to the control group." (PMID 29581524, 2018).
alopecia (2 papers, 2021 to 2023). Hair loss usually from the scalp. "Loss of DNA-methyltransferase 1 (DNMT1) in the developing epidermis results in improper HF architecture and progressive alopecia in aged animals." (PMID 34905545, 2021). "Genetic deletion of DNA methyltransferase 1 (DNMT1), on the other hand, decreases HF-SC activation and leads to progressive alopecia." (PMID 37465120, 2023).
ameloblastoma (2 papers, 2021). The most common odontogenic tumor, arising from the epithelial component of the embryonic tooth and usually affecting the molar-ramus region of the mandible or maxilla. "The ameloblastomas with BRAFv600e mutation, vestibular/lingual, or vestibular/palatine bone cortical disruption and maxilla involvement showed DNMT1 overexpression, while recurrent cases had high DNMT3B levels." (PMID 35048062, 2021). "The expression of DNMT1 in ameloblastomas can deregulate the role of p27 in cellular biological processes." (PMID 33680332, 2021). "This study aimed to describe the immunohistochemical expression of DNMT1, DNMT3A, DNMT3B, and H3K9ac in the dental follicle (DF), ameloblastoma (AME), and ameloblastic carcinoma (AC), correlating these expressions with the recurrence and aggressive behavior in ameloblastoma." (PMID 35048062, 2021). "Therefore, we aimed to investigate DNMT1, DNMT3A, DNMT3B, and H3K9ac immunohistochemical expression in the most prevalent and locally aggressive benign odontogenic tumor, ameloblastoma, and compare this with its malignant counterpart, ameloblastic carcinoma (AC)." (PMID 35048062, 2021).
and autonomic neuropathy (2 papers, 2016 to 2017). "In the PNS, mutations in DNA methyltransferase 1 cause a form of hereditary sensory and autonomic neuropathy through aberrant DNA methylation." (PMID 28903050, 2017).
astrocytoma (2 papers, 2010 to 2021). "Next, the effects of DNMT1 knockdown on in vivo growth of astrocytoma cells was examined using a nude mice model." (PMID 34858853, 2021). "Moreover, the existence of (a) molecular mechanism(s) inhibiting the Dnmt1/PCNA/UHRF1 interaction is also supported by the paradoxical situation seen in astrocytoma cells." (PMID 20613874, 2010). "Therefore, inhibition of DNMT1 activity inhibited the subcutaneous growth of astrocytoma cells." (PMID 34858853, 2021). "Therefore, inhibition of DNMT1 activity inhibited the invasion of astrocytoma cells in vitro." (PMID 34858853, 2021). "The results revealed that the DNMT1-mediated hypermethylation of the miR-338-5p promoter region could participate in the loss of miR-338-5p expression and the high expression of ETS1 associated with disease severity in astrocytoma patients." (PMID 34858853, 2021). "Indeed, the astrocytoma cells harbor a low level of Dnmt1/PCNA/UHRF1 interaction, whereas these cells, highly proliferative, are supposed to harbor a high level of the Dnmt1/PCNA/UHRF1 interaction according to the idea that the maintenance DNA methylation is a DNA replication-dependent process." (PMID 20613874, 2010). "Knockdown or deactivation of DNMT1 decreased the methylation rate of the miR-338-5p promoter, increased the expression of miR-338-5p, and repressed the expression of ETS-1 in astrocytoma cell lines U251 and U87." (PMID 34858853, 2021).
biliary atresia (2 papers, 2017 to 2018). A rare, biliary tract disease characterized by progressive obliterative cholangiopathy of the intra- and extrahepatic bile ducts, occurring in the embryonic/ perinatal period, leading to severe and persistent neonatal jaundice and acholic stool. "Our study showed that DNMT1, DNMT3a, and DNMT3b expression is significantly decreased, while the expression level of IFN-γ is increased in liver samples of biliary atresia cases." (PMID 29748604, 2018).
breast ductal carcinoma in situ (2 papers, 2025 to 2026). "This study reveals that miR‐217 suppresses breast ductal carcinoma in situ (DCIS) by targeting DNMT1, reducing TSHZ2 promoter methylation and restoring TSHZ2 expression." (PMID 40909350, 2025).
cardiomyopathies (2 papers, 2021 to 2025). "The cardiomyopathy-associated targets were Dnmt1, Hdac1, Dot1l, Setd5, Nsd2, Usp3, Bap1, Prkca, Prkcb, Crebbp and Clock: 11 out of 81 (13.6% of total targets)." (PMID 40076868, 2025). "The patient was a heterozygous carrier of VUS in DNA methyltransferase 1 (DNMT1) gene (c.1043C> T), and VRK serine/threonine kinase 1 (VRK1) gene (c.8G>A), in addition to dynamin 2 (DNM2) gene (c.2576_2578delCCA), which is associated with severe cardiomyopathies." (PMID 33567613, 2021).
chronic hepatitis (2 papers, 2019 to 2025). An active inflammatory process affecting the liver for more than six months. "The number of methylated genes and the mRNA levels of DNMT1, DNMT3a and DNMT3b were shown to be increased progressively from normal liver, chronic hepatitis/cirrhosis to HCC." (PMID 31771617, 2019). "The upregulation of DNMT1 was detected in noncancerous liver tissues showing chronic hepatitis or cirrhosis, and it was further upregulated in HCC tissues." (PMID 40761482, 2025).